CMTM4 (CKLF like MARVEL transmembrane domain containing 4)
Diseases named in the same sentence as CMTM4 in open-access papers (continued):
Sharing a sentence is not in itself a finding about the gene and the disease.
tumor (continued). "Our findings suggest that CMTM4 is a novel intrinsic molecule that can be targeted to reverse the immune-suppressive tumor microenvironment and improve efficacy of chemotherapy and immunotherapies." (PMID 39948411, 2025). "To explore this, we analyzed the association between CMTM4 expression and CD45+ tumor‐infiltrating leukocytes (including CD68+ macrophages, CD19+ B cells, CD8+ T cells, and FOXP3+ regulatory T cells [Tregs]) in the TCGA‐OC cohort." (PMID 40433989, 2025). "Taken together, these findings demonstrate that targeting tumor‐derived CMTM4 can alleviate chemoresistance and enhance the efficacy of immunotherapy, thereby strongly enhancing current OC treatments." (PMID 40433989, 2025). "In contrast, CD8 cells were significantly increased in CMTM4 KD tumors, suggesting an important role of T cells contributing to the reduced growth of CMTM4 KD/KO tumor." (PMID 39948411, 2025). "Overall, these results suggest that CMTM4 was highly expressed in multiple cancer types, correlates with tumor progression, and its expression can be a poor prognostic factor in multiple cancer types." (PMID 39948411, 2025). "The results showed the efficacy of CMTM4 inhibition in suppressing tumor growth and metastasis and demonstrated the potential of inhibiting CMTM4 as a novel cancer treatment." (PMID 39948411, 2025). "Hematoxylin‐Eosin staining showed that the presence of CMTM4 in tumor tissue increased atypical cell production, and Immunofluorescence (IF) staining confirmed a significant reduction in Ki67‐ and CD44‐positive (invasive marker) regions in ID8/CMTM4 KO tumors." (PMID 40433989, 2025). "Our data suggests CMTM4 is a novel regulator of the EGFR/AKT/mTOR pathway in human tumor and affects sensitivity to EGFR tyrosine kinase inhibition." (PMID 39948411, 2025). "Collectively, these results identify ELT as a potent small‐molecule inhibitor of CMTM4, with notable anti‐tumor activity." (PMID 40433989, 2025). "Collectively, the study highlights the critical role of tumor‐derived exosomal CMTM4 in immune suppression, emphasizing its potential as both a prognostic biomarker and a therapeutic target in OC immunotherapy." (PMID 40433989, 2025). "Taken together, exosomal CMTM4 serves as a key mediator between tumor cells and the TIME, promoting OC progression." (PMID 40433989, 2025). "CMTM4 deficiency reduced TAM infiltration, and macrophage depletion phenocopied its tumor‐suppressive effects, while TAM supplementation restored tumor growth." (PMID 40433989, 2025). "Depletion of the tetra-transmembrane protein CMTM4 sensitizes tumor cells to EGFR inhibition and limits tumor growth by reducing the production of inflammatory cytokines and the recruitment of immune-suppressive cells." (PMID 39948411, 2025). "In this study, we investigated the role of exosomal CMTM4 in the OC microenvironment, with a particular focus on its effects on M2 macrophage polarization, immunosuppression, and tumor progression." (PMID 40433989, 2025). "Our results further indicate that CMTM4 controls oncogenic pathways, RTKs, to alter the tumor immune microenvironment." (PMID 39948411, 2025). "While previous studies have explored how various molecular signals facilitate TAM‐tumor cell interactions, the specific role of exosomal proteins—such as CMTM4—in reprogramming TAMs toward an M2‐like phenotype has remained largely unexplored." (PMID 40433989, 2025). "CMTM4 can effectively protect programmed death-ligand 1 (PD-L1) as a target for lysosomal degradation and prevent the clearance of tumor cells by immune cells, suggesting that CMTM4 plays an important role in tumor immunotherapy." (PMID 38223763, 2024). "As the most conserved member of the CMTM family, CMTM4 is frequently downregulated and regulates cell growth and cell cycle to exert tumor-suppressing activity in several cancers, including RCC, by inhibiting the AKT and ERK pathways." (PMID 35220395, 2022).
tumor (continued). "In conclusion, overexpression of miR-421 and silencing of CMTM4 reversed tumor suppression induced by circCYP24A1 expression." (PMID 35220395, 2022). "CMTM6 and CMTM4 are novel proteins found to promote tumor progression by stabilizing PD-L1 in recent and ongoing research." (PMID 35958549, 2022). "Generally, we confirmed CMTM4 as a tumor suppressor in RCC and a downstream target of circCYP24A1/miR-421." (PMID 35220395, 2022). "786-O-luc cells transfected with LV-NC, LV-circCYP24A1, LV-circCYP24A1 plus miR-421 mimic, and LV-circCYP24A1 plus sh-CMTM4 were subcutaneously injected into nude mice and tumor growth was evaluated." (PMID 35220395, 2022). "Colony-formation assays and Transwell assays further showed that miR-421 overexpression and CMTM4 silencing promoted tumor proliferation and invasion after circCYP24A1 overexpression." (PMID 35220395, 2022). "Compared to each molecule alone, the co-expression of CMTM6 and PD-L1, CMTM6 and CMTM4 in the tumor epithelial region showed better prognostic value in the patients with GC." (PMID 34680324, 2021). "CMTM4 and its homolog CMTM6 encode transmembrane proteins that positively regulate the PD-L1 protein pool in human tumor cells and dendritic cells." (PMID 32117236, 2020). "The level of CMTM4 expression was negatively correlated with the tumor size, the clinical (TNM) stage and the presence of metastasis." (PMID 32944388, 2020). "The in vitro experiments demonstrated that CMTM4 exhibited antitumourigenic activities in ccRCC; therefore, we subsequently used a xenograft model in nude mice to confirm the ex vivo tumour-suppressor activity of CMTM4." (PMID 26474560, 2015). "CMTM4 is a member of this family and is located at chromosome 16q22.1, a locus that harbours a number of tumour suppressor genes." (PMID 26474560, 2015). "The expression of CMTM4 was frequently downregulated in ccRCC tissues (53/61, 86.9 %) compared to the matched adjacent non-tumour tissues." (PMID 26474560, 2015). "Since the adaptive immune response is required for the reduced tumor growth with CMTM4 KD/KO cancer cells, we hypothesized that cytokine profile differences between control and CMTM4 KD/KO cells may contribute to different immune responses." (PMID 39948411, 2025). "Elucidating the molecular mechanisms by which CMTM4 drives M2 polarization may offer valuable insights for the development of innovative therapeutic strategies targeting the tumor immune microenvironment (TIME) in OC." (PMID 40433989, 2025). "In contrast to the in vitro findings, silencing CMTM4 significantly inhibited tumor growth in vivo." (PMID 40433989, 2025). "We further determined whether CMTM4 expression was increased in human carcinomas by comparing CMTM4 expression levels between tumor and normal tissue with same origin in multiple human cancer types from the TCGA and Genotype Tissue Expression (GTEx) databases." (PMID 39948411, 2025). "Indeed, we found that CMTM4 KD tumor was more responsive to PD-L1 antibodies treatment, which is resulted from reduced inflammatory cytokines productions from CMTM4 KD cells with retarded EGFR signaling." (PMID 39948411, 2025). "However, CMTM4 KO cells show elevated sensitivity to gefitinib treatment, indicating CMTM4 plays a role in tumor intrinsic resistance to EGFR tyrosine kinase inhibitors." (PMID 39948411, 2025). "Targeting CMTM4 with drugs or RNA interference restores anti‐tumor immunity and improves prognosis." (PMID 40433989, 2025). "Interestingly, the combination of CMTM4 KD and anti-PD-L1 antibody treatment further inhibited tumor growth in vivo." (PMID 39948411, 2025). "Human carcinoma tissues and murine tumor cell lines expressed high levels of CMTM4." (PMID 39948411, 2025). "Moreover, we found that CMTM4 is significantly associated with epithelial-mesenchymal transition (EMT) gene signatures, suggesting that CMTM4 can be a biomarker for tumor metastasis." (PMID 39948411, 2025).
tumor (continued). "We confirmed that knockdown of CMTM4 resulted in reduced angiogenesis in tumor tissues." (PMID 39948411, 2025). "Furthermore, MDSCs showed increased M1-like anti-tumor functional phenotype and reduced M2-like pro-tumor phenotype in CMTM4 KO tumor-bearing mice." (PMID 39948411, 2025). "Indeed, we found significant reductions of PMN (Gr-1HighLy6CLow) MDSCs in the tumors, bone marrow and spleen, from CMTM4 KD tumor-bearing mice when compared to mice bearing control tumor with a similar tumor size." (PMID 39948411, 2025). "Interestingly, proteins that reduce Erk1/2 activation, such as CMTM4, have shown anti-tumor effects in CRC and other types of cancer." (PMID 37275957, 2023). "Gene-set enrichment analysis showed that CMTM4 expression was negatively associated with the MAPK signaling pathway, suggesting that CMTM4 may regulate this pathway to suppress tumor progression." (PMID 35220395, 2022). "Therefore, the interaction between CMTM4 and PD-L1 made a significant impact on tumor microenvironment through targeting CD4 T cells, and then promoted the malignant progression of HCC." (PMID 35986302, 2022). "However, CMTM4 has also been reported to play a tumor suppressor role in some tumors, which can inhibit cell proliferation in clear cell renal cell carcinoma and colorectal cancer." (PMID 35958549, 2022). "Therefore, circCYP24A1 overexpression inhibited tumor progression in vivo through the miR-421/CMTM4 pathway." (PMID 35220395, 2022). "CMTM4 is considered as a tumor suppressor in multiple cancers including CRC." (PMID 35814269, 2022). "Thus, we suggested that circCYP24A1 overexpression suppressed tumor metastasis in vivo by regulating the circCYP24A1/miR-421/CMTM4 network in RCC." (PMID 35220395, 2022). "It has been shown that CMTM4 is a tumor suppressor in human cancers, including CRC." (PMID 35814269, 2022). "The CMTM4 gene is located on chromosome 16q22.1, a locus including numerous tumor suppressor genes." (PMID 32944388, 2020). "CMTM4 is frequently downregulated and act as a tumor-suppressor." (PMID 33282744, 2020). "CMTM3 and CMTM4 genes are closely located at the tumor suppressor locus 16q22.1." (PMID 33282744, 2020). "Thus, restoration of CMTM4 suppresses the tumorigenicity of these cancer cells, whereas knockdown of CMTM4 leads to enhanced tumor growth." (PMID 30097810, 2019). "CMTM4 has been identified as a regulator of PD-L1 protein stability in tumor cells." (PMID 31143705, 2019). "Overexpression of CMTM4 also markedly inhibited the tumour xenograft growth in nude mice." (PMID 26474560, 2015). "CMTM4 is downregulated and exhibits tumour-suppressor activities in ccRCC, and could be exploited as a target for ccRCC treatment." (PMID 26474560, 2015). "Compared to the non-tumour tissue, CMTM4 was dramatically downregulated in the ccRCC tissue." (PMID 26474560, 2015). "Moreover, expression of CMTM4 is not suppressed in carcinoma tissues, even though CMTM4 is closely associated with the tumor suppressor locus 16q22.1, which is frequently deleted in multiple tumors." (PMID 39948411, 2025). "Therefore, loss of CMTM4 in tumor cells decreased EGFR signaling, and hence, decreased G-CSF production and PMN-MDSCs recruitment, which led to a less suppressive tumor immune microenvironment and reduced tumor growth." (PMID 39948411, 2025). "However, there are only a few studies to clarify the relationship between CMTM4 and tumor immunity." (PMID 35986302, 2022). "Therefore, the upregulation of p21 may be responsible for the tumour suppressor functions of CMTM4 in 786-O cells." (PMID 26474560, 2015). "CKLF-like MARVEL transmembrane domain-containing 4 (CMTM4), a member of the CMTM family, has emerged as a regulator of tumor immune regulation and membrane protein trafficking." (PMID 42254028, 2026). "This study shows that inhibiting the function of the tetra-transmembrane protein CMTM4 can sensitize tumor cells to EGFR inhibition and restrict tumor growth by repressing tumor inflammation." (PMID 39948411, 2025).
tumor (continued). "We further performed cytokine array analyses with tumor cells stimulated with EGF and found increased protein levels of G-CSF, GM-CSF, and CCL-1 in control cells compared to CMTM4 KD cells." (PMID 39948411, 2025). "In summary, CMTM4 prevents EGFR from lysosomal degradation, which further amplifies EGFR signaling and activation of the Akt/mTOR/NF-κB pathways to promote tumor growth." (PMID 39948411, 2025). "Collectively, these findings establish CMTM4 as a key orchestrator of the TIME, promoting immune evasion and tumor progression via TAM modulation." (PMID 40433989, 2025). "By inhibiting CMTM4, ELT synergized with PD‐1 blockade, resulting in marked tumor suppression and prolonged survival in treated mice." (PMID 40433989, 2025). "Analysis of TCGA‐OC cohort revealed a strong correlation between CMTM4 expression and CD68+ macrophage infiltration, which was further validated in both human and murine tumor samples." (PMID 40433989, 2025). "Here, we provide new insights into how exosomal CMTM4 modulates TAM polarization, activates NF‐κB signaling, and promotes the secretion of immunosuppressive cytokines and chemokines, thereby driving tumor progression and metastasis." (PMID 40433989, 2025). "Surprisingly, multiple previously reported tumor suppressors of KIRC were found in these downregulated genes, including SOX6, DAPK1, PDZK1, TXNIP, DAB2IP, and CMTM4." (PMID 37737260, 2023). "In summary, CMTM6 and CMTM4 play important roles in the TME through regulating PD-L1, immune cells, tumor cells and different components of TME." (PMID 35958549, 2022). "For example, it has been proven that CMTM3, CMTM4, CMTM5 and CMTM7 are new potential tumor suppressors, and interestingly, patients with high CMTM6 expression have a worse survival prognosis than those with low CMTM6 expression according to this study." (PMID 35983975, 2022). "The roles of CMTM6 and CMTM4 in regulating TME components, including immune cells and tumor cells themselves were discussed in this review." (PMID 35958549, 2022). "As found in other studies, CMTM4 plays a tumor-suppressor role in HCC, wherein it inhibits tumor activities by regulating cell growth and cell cycle." (PMID 34917619, 2021). "Indeed, our results demonstrate that the co-expression of CMTM6 or CMTM4 with PD-L1 on the membrane of tumor cells is critical for immunotherapeutic response and the pathological patterns of their expression may provide detailed information to conduct personalized immunotherapy." (PMID 34680324, 2021). "Consistent with our previous publication demonstrating the role of MDSCs in Treg cell expansion in tumor-bearing mice, we observed that Treg cells and the CD4 population were significantly reduced in CMTM4 KD tumors when compared to mice bearing control wild-type tumors." (PMID 39948411, 2025). "We found that inhibition of CMTM4 in cancer cells reduced tumor growth in vivo but not in vitro, which suggests that CMTM4 is an important regulator in the establishment of the suppressive and pro-tumor microenvironment." (PMID 39948411, 2025). "A series of quantitative RT-PCR assays confirmed that the expression of CMTM4 was significantly higher in tumor cell lines than in the normal tissues analyzed." (PMID 39948411, 2025). "CMTM4 regulates RTK function and further controls downstream signal activation, including NF-κB and Akt/mTOR pathways, which may induce tumor productions of various cytokines and chemokines in cancer cells, including CCL-1, IL-1β, G-CSF." (PMID 39948411, 2025). "Exosomal CMTM4 engages macrophages via ICAM1, enhancing cancer cell–macrophage interactions, facilitating p65 nuclear translocation, and promoting M2 polarization, thereby driving tumor progression." (PMID 40433989, 2025). "In contrast to a previous finding that CMTM4 inhibited HeLa cell growth by inducing G2/M phase arrest, we found that CMTM4 knockdown did not affect the proliferation of tumor cells in vitro." (PMID 39948411, 2025).
tumor (continued). "Several studies have identified CMTM4 as a tumor suppressor in various types of malignant lesions, while the regulatory role of CMTM4 in RCC has not been studied." (PMID 35220395, 2022). "Recently, CMTM4 and CMTM6 are identified as PD-L1 regulators to regulate PD-L1 stability during the immune process in many tumor cells, and thus expected to be a new target for tumor immunotherapy." (PMID 35986302, 2022). "Unlike pattern 1, the intensity of CMTM6 and CMTM4 expression in pattern 2B was lower and was mainly found in the cytoplasm of tumor epithelial cells." (PMID 34680324, 2021). "The tumor tissues had elevated levels of CMTM6, CMTM4, and CD274 (PD-L1) transcripts." (PMID 34680324, 2021). "CMTM4 is the most conserved member of this family and forms a gene cluster with CKLF and CMTM1-3 on chromosome 16q22.1, a locus that is frequently deleted or modified in multiple tumours and that harbours a number of tumour suppressor genes." (PMID 26474560, 2015). "Therefore, CMTM4 represents a novel target for reversing the tumor-promoting phenotype of MDSCs without directly eliminating these cells." (PMID 39948411, 2025). "Since we found significant reduced tumor growth with CMTM4 KD/KO cancer cells in vivo but not in vitro, we determined whether the immune response, especially the adaptive immunity, is required for the retarded tumor growth." (PMID 39948411, 2025). "Notably, ID8/CMTM4 KO bearing mice lacking TAMs demonstrated the lowest tumor burden and the longest survival." (PMID 40433989, 2025). "In one study, CMTM4 expression was found specifically in cancerous cells in 21 (28.00%) of 75 cases, but 49 (65.33%) of the 75 adjacent nontumor tissues, in agreement with its tumor-suppressive effect." (PMID 32944388, 2020). "In SW480 cells, CMTM4 expression was found to be inversely related to the phosphorylation of AKT1, and the tumor-suppressive functionalities observed with CMTM4 overexpression could be mimicked in the CMTM4- SW480 cell line by direct chemical inhibition of AKT using LY294002." (PMID 33614606, 2020). "Therefore, unlike other CMTM family members, CMTM4 might not have a tumor suppressor role in certain cancers." (PMID 39948411, 2025). "However, the role of CMTM4 in tumor immunity has not been well clarified, especially in HCC." (PMID 35986302, 2022). "The discrepancy between CMTM4's in vivo and in vitro effects suggests that its primary role is in modulating TIME, rather than acting directly on tumor cells." (PMID 40433989, 2025). "Results showed that there is a significant association between CMTM6 expression and Ki67 expression/recurrence, while CMTM4 expression is not significantly different between patients with clinically-related factors, indicating that CMTM6 may play an important role in tumor genesis and development." (PMID 35983975, 2022).